AXIN2 (axin 2)
Diseases named in the same sentence as AXIN2 in open-access papers (continued):
Sharing a sentence is not in itself a finding about the gene and the disease.
breast cancer (continued). "In the current study, we investigated the interactions between SOX7 and AXIN2 in their co-regulation on the Wnt/β-catenin signal pathway, using clinical specimens and microarray gene expression data from the GEO database, for their roles in breast cancer." (PMID 27188720, 2016). "In conclusion, we demonstrate here, for the first time, that SOX7 plays the role of tumor suppressor on β-catenin by targeting Smad7, together with AXIN2 as a portential co-regulator of the Wnt/β-catenin signaling pathway in controlling breast cancer progression." (PMID 27188720, 2016). "Furthermore, we checked the protein level of MUC16, β-catenin and three Wnt downstream genes, Snail, Axin2 and Cyclin D1 in three sets of human breast cancer samples by Western blot." (PMID 27167110, 2016). "In breast cancer, several lines of evidence have implicated overexpression of EZH2 and repression of tumor suppressors such as KRT5, KRT6, CDH3, RAD51 paralogs, CDKN1C, FOXC1, Wnt/β-catenin signaling (c-Myc, Cyclin D1, Axin2), RKIP and KLF2." (PMID 27835578, 2016). "Addition of IWP-2 reduced DKK1 and AXIN2 expression in tamoxifen resistant breast cancer cells." (PMID 24178749, 2014). "We did not observe statistically significant association with the risk of developing breast cancer for the SNPs in APC, DKK4 and LRP6 as well as some of the SNPs in β-catenin (rs13072632), AXIN2 (rs4791171, rs11079571 and rs3923086) and SFRP3 (rs288326) in the overall study population." (PMID 23516639, 2013). "However, given the body of literature linking Wnt signaling to breast cancer, we measured the expression of Axin2 in mammary tissue of control and Sfrp1-/- mice fed a ND or HFD because it is a direct readout of Wnt signaling." (PMID 24339864, 2013). "Moreover, their results revealed that AXIN2 rs3923086 has a protective influence in breast cancer patients older than 43 years and AXIN2 rs3923087 heterozygous AG genotype was associated with reduced risk in both the age groups (≤43 or >43) as well as in the overall study." (PMID 34452579, 2021). "There was no a significant association between the AXIN2 SNP and risk of breast cancer." (PMID 34452579, 2021). "Genes such as FGFR1, WNT10A, AXIN2, and LRP6—known contributors to tooth agenesis—also play established roles in breast cancer pathophysiology, suggesting shared mechanisms of aberrant signaling." (PMID 41226524, 2025). "In breast cancer, MYB acts as a promoter of breast cancer metastasis via activating the Wnt/β-catenin/Axin2 signaling pathway." (PMID 36994664, 2023). "Treatment with buparlisib (PI3Kα/β/δ/γ inhibitor) reduced the expression of Wnt target genes AXIN2, LEF1, and MYCN in human PIK3CA-mutant ER+ breast cancer cells." (PMID 37471270, 2023). "Our data showed that YTHDF1 knockdown distinctly lowered the expression of Axin2, c-myc, β-catenin, and cyclin D1 in MCF-7 cells, confirming that YTHDF1 participated in the activation of WNT pathway in breast cancer." (PMID 34434939, 2021). "Endocrine-sensitive or -resistant breast cancer cell lines were used to examine the expression of the stem cell gene SOX2, and the Wnt effector genes AXIN2 and DKK1 using quantitative PCR analysis." (PMID 28929082, 2017). "Spearman’s rank order correlation coefficients of relative gene expression values for SOX2, AXIN2, and DKK1 in breast cancer samples from The Cancer Genome Atlas (TCGA_BRCA_exp_HiSeqV2-2015-02-24) data set (n = 1,009), *p < 0.05." (PMID 28929082, 2017). "It turned out that, the protein levels of β-catenin, Snail, Axin 2 and Cyclin D1 in the carcinoma tissue (C) were elevated along with MUC16 in the number 1 and number 2 breast cancer samples, compared with the counterparts of normal tissue (N)." (PMID 27167110, 2016). "Well established downstream targets, AXIN2 and LEF1 showed higher expression in breast cancer cell lines suggesting activation of canonical WNT signalling." (PMID 23861811, 2013).
breast cancer (continued). "Unlike in breast cancer samples, Wnt activity determined by Axin2 was inversely correlated to YAP-mediated transcriptional activity in CRC samples, particularly in APC or CTNNB1 mutated cancer samples." (PMID 34298652, 2021). "In breast cancer cells, knockout of TMEM97 attenuated the Wnt/β-catenin signaling cascade via regulating LRP6 phosphorylation, leading to a decrease in the expression of Wnt target genes AXIN2, LEF1, and survivin." (PMID 34615853, 2021). "Increased mRNA expression of AXIN2 (1.9-fold), LEF1 (2.3-fold), and DKK1 (3.2-fold) was also observed in T47D cells expressing GFP-INPP4B, demonstrating that INPP4B enhances Wnt/β-catenin signaling in PIK3CA-mutant ER+ breast cancer cells." (PMID 34035258, 2021). "In breast cancer MDA-MB-231 and MDA-MB-468 cells, treatment with gigantol reduced the level of phosphorylated LRP6, total LRP6 and cytosolic β-catenin in a dose-dependent manner, resulting in a decrease in the expression of Wnt target genes Axin2 and Survivin." (PMID 29444668, 2018). "In breast cancer cells, gigantol treatment significantly decreased the levels of phosphorylated LRP6, total LRP6 and cytosolic β-catenin, resulting in a decrease in the expression of Wnt target genes Axin2 and Survivin." (PMID 29444668, 2018). "Spearman’s rank order correlation coefficients of relative gene expression values (fold change) for AXIN2, DKK1, and SOX2 versus IC50 value of the WNT inhibitors LGK974 and IWP-2 in MCF-7 parental and endocrine therapy-resistant breast cancer cell lines (n = 14)." (PMID 28929082, 2017). "Furthermore, the consistent expression of other markers such as nuclear β-catenin, Axin2, CK5 and CK6, and a specific subset of cell cycle regulators demonstrate the high similarity of the mouse and human TN mammary tumours." (PMID 23307470, 2013). "Moreover, WNT1, WNT4, AXIN2 and LEF1 are upregulated and high β-catenin activity is significantly correlated with poor prognosis in breast cancer patients." (PMID 23516639, 2013). "In MMTV.neu mammary tumors in which the Wnt/β-catenin pathway is not involved, expression of Axin2 was extremely low (relative expression 0.01 compared to BK5.ATF3 mammary glands, p<0.01, data not shown), and Dkk4 was undetectable." (PMID 21304988, 2011). "Similar effects were also observed in canine mammary cancer cell lines that exhibit high basal Wnt/β-catenin activity, where treatment with dactolisib (dual pan-PI3Kα/γ/δ/β and mTOR inhibitor) enhanced TCF/LEF transcriptional activity, and CTNNB1 and AXIN2 mRNA expression." (PMID 37471270, 2023). "Based on the findings in this study, we propose that the significantly reduced expression of both SOX7 and AXIN2 may jointly facilitate the pathogenesis of breast cancer, possibly through regulating the β-catenin by not-direct as well as direct ways." (PMID 27188720, 2016). "The results show that high expression of TCF7, AXIN2 and WIF1 all predict shorter relapse-free survival (RFS) in HER2-amplified breast cancer, but longer RFS in HER2-non-amplified disease." (PMID 34003256, 2021). "Independent of ER status, overall WNT pathway signalling assessed by the canonical downstream target genes AXIN2 and LEF1 is higher in breast cancer cell lines compared to normal breast cell lines." (PMID 23861811, 2013). "Analysis of The Cancer Genome Atlas database showed that, unlike primary PIK3CA‐wild‐type and HER‐2+ breast carcinomas, PIK3CA‐mutant tumors display increased expression of AXIN2, HGF, STAT3, IGF‐1, and IGF‐2 mRNA and activation of AKT, IGF1‐MTOR, and WNT canonical signaling pathways." (PMID 28296140, 2017). "Besides, AXIN2, PLAG1, GPC3, DICER1 are not connected with any breast cancer genes." (PMID 31760937, 2019).
tooth agenesis (45 papers, 2012 to 2025). A tooth disease characterized by failure to develop one or more missing teeth. "As PAX9, MSX1, and AXIN2 are most frequently associated with non-syndromic hypodontia, we studied these specific genes." (PMID 39183201, 2024). "Tooth agenesis is associated with several genes; however, non-syndromic human tooth agenesis has been associated with mutations in AXIN2, EDA, PAX9, MSX1, and PAX9." (PMID 39156431, 2024). "Our study identified an association between AXIN2 and hypodontia in the studied population and highlighting the importance of utilizing machine learning in hypodontia research." (PMID 39183201, 2024). "Multivariate logistic regression indicated a significant association between homozygous AXIN2 rs2240308 and the hypodontia phenotype (ORs [95% confidence interval] 2.893 [1.28–6.53])." (PMID 39183201, 2024). "In this study, we initially examined the genotype distribution and allele frequency of SNPs of the MSX1, PAX9, and AXIN2 genes that were previously identified in GWAS as being associated with hypodontia susceptibility." (PMID 39183201, 2024). "Here, we report a family with a novel frameshift germline mutation in exon 8 of AXIN2 associated with colorectal polyposis and hypodontia." (PMID 37626374, 2023). "In patients with severe familial hypodontia, direct sequencing of the AXIN2 gene revealed a nonsense mutation (Arg656Stop) in exon 7, which led to premature translation termination." (PMID 37762190, 2023). "Here we describe the novel heterozygous pathogenic frameshift variant R671Pfs*36 in exon 8 of the AXIN2 gene in a 55-year-old man with polyposis and hypodontia." (PMID 37626374, 2023). "Mutations in PAX9, MSX1, WNT10A, and AXIN2 genes are most commonly associated with non-syndromic tooth agenesis in the literature." (PMID 36561383, 2022). "Segregation analysis showed that the mother, the maternal grandfather, and the maternal aunt were carriers of the AXIN2 variant and presented with hypodontia." (PMID 32234057, 2020). "Additional common variants in AXIN2 have also been associated with increased susceptibility to hypodontia in Eastern Europeans." (PMID 31781599, 2019). "In the remaining five AXIN2 mutations causing non-syndromic tooth agenesis, four are missense mutations (p.Ala758Thr, p.Ala684Val, p.Thr308Met and p.Met830Ile), and one is a frameshift mutation (p.Gly666GlyfsX42)." (PMID 26406231, 2015). "To date, four studies reported seven AXIN2 mutations associated with syndromic or non-syndromic tooth agenesis." (PMID 26406231, 2015). "Paradoxically, loss of AXIN2, which codes for a protein belonging to the same destruction complex, has an opposite effect, and leads to severe hypodontia." (PMID 25339911, 2014). "Conversely, multivariate logistic regression analysis offers greater power and control over variables and revealed a significant association between AXIN2 gene variations and non-syndromic hypodontia, corroborating the genetic risk assessment for the hypodontia group." (PMID 39183201, 2024). "It is conceivable that defects in other genes, in addition to AXIN2, involved in Wnt signalling and regulation of ß-catenin level may also show a link between tooth agenesis and cancer predisposition." (PMID 25810703, 2015). "This indicates that any change in the AXIN2 protein can cause severe tooth agenesis." (PMID 26406231, 2015). "In addition, this study extends the mutation spectrum of the AXIN2 gene in individuals with non-syndromic tooth agenesis." (PMID 26406231, 2015). "Tooth agenesis is typically caused by genetic mutations in MSX1, PAX9, and AXIN2 that affect tooth development." (PMID 40136761, 2025). "Individuals in the hypodontia group were more likely to possess a homozygous AXIN2 rs2240308 (OR [95% confidence interval] 2.893 [1.28–6.53])." (PMID 39183201, 2024). "In this study, we investigated the use of machine learning to predict hypodontia risk based on selected SNPs in the MSX1, PAX9, and AXIN2 genes." (PMID 39183201, 2024).
tooth agenesis (continued). "In studies involving Brazilian and Turkish patients with selective tooth agenesis, three intragenic polymorphic sites (rs7591, rs11867417, and rs2240308) in the AXIN2 gene were analyzed." (PMID 37762190, 2023). "Mutations in several genes have been associated with familial tooth agenesis, among others MSX1, PAX9, AXIN2, EDA, EDARADD, and EDAR." (PMID 33743023, 2021). "Mutations of several genes such as PAX9, MSX1, AXIN2, KDF1 and WNT10A have been reported which are associated with non-syndromic tooth agenesis." (PMID 33014315, 2020). "Among several genes involved in tooth development, mutations in MSX1, PAX9, AXIN2, WNT10A, EDA and KDF1 have been reported to play a role in tooth agenesis 6–13." (PMID 33014315, 2020). "Mutations in several genes have been associated with nonsyndromic tooth agenesis, among others the PAX9, MSX1, AXIN2, EDA, EDARADD, and EDAR genes." (PMID 32234057, 2020). "Research has identified an association between mutations in MSX1, PAX9, EDA, AXIN2, WNT10A, WNT10B and LRP6 and human tooth agenesis." (PMID 31914153, 2020). "This fact, remark the importance to identify biomarkers for CRC in population, such as AXIN2 variations in patients with Hypodontia." (PMID 31632692, 2019). "The genetic polymorphism of axin 2 (AXIN2) and Gremiln-2 (GREM2, also called PRDC) were related with tooth agenesis." (PMID 31133012, 2019). "Most often reported genes associated with nonsyndromic tooth agenesis are PAX9, MSX1, EDA, and AXIN2." (PMID 31781599, 2019). "Most often reported genes associated with the familial form of the nonsyndromic tooth agenesis are paired box gene 9 (PAX9), Msh homeobox 1 (MSX1), ectodysplasin A (EDA), and axis inhibitor protein 2 (AXIN2)." (PMID 31781599, 2019). "Among these genes, PAX9 (paired box gene 9), MSX1 (muscle segment homeobox 1), AXIN2 (axis inhibition protein 2), and EDA (ectodysplasin A) are the most frequently reported genes associated with nonsyndromic hypodontia." (PMID 28401166, 2017). "Mutations and genetic variants of this pathway, such as WNT10A, AXIN2 and LRP6, have all been well recognized as susceptibility factors of tooth agenesis." (PMID 27362534, 2016). "The nature of this association would be better determined by genetic investigations in humans, taking into consideration the different pathways of PAX9, MSX1, and AXIN2 acting on both hypodontia and delayed dental development." (PMID 26462655, 2016). "The proband was screened for mutations of genes previously related to tooth agenesis (i.e., PAX9, AXIN2, EDA, WNT10A, etc.)by targeted exome sequencing (TES), with next generation technology." (PMID 27917906, 2016). "The most significant association was for a missense mutation in exon 10 (P50S, rs2240308) with a p-value of 0.037, and they concluded that their work provided further evidence that AXIN2 contributes to tooth agenesis." (PMID 24607150, 2014). "At present, mutations causing non-syndromic tooth agenesis have been identified in MSX1, PAX9, AXIN2, EDA, and WNT10A." (PMID 23227268, 2012). "Our study confirms a link between AXIN2 and hypodontia in Saudi orthodontic patients and suggests that combining machine-learning models with SNP analysis of saliva samples can effectively identify individuals with non-syndromic hypodontia." (PMID 39183201, 2024). "Congenital tooth agenesis is caused by mutations in the MSX1, PAX9, WNT10A, or AXIN2 genes." (PMID 26030286, 2015). "When considering isolated cases or the nonsyndromic form, many studies have investigated the correlation between tooth agenesis and genetic mutations present in individuals belonging to one and the same family, attributing the mutations to genes PAX9, MSX1, AXIN2, and EDA." (PMID 25215247, 2014). "The mode of transmission of hypodontia due to defects in the AXIN2 gene has not been definitively proven, and it has been seen that individuals with a non-sense mutation in AXIN2 display a mixed pattern of dental agenesis." (PMID 24121910, 2014).
tooth agenesis (continued). "However, among those 119 sequence variants a c.956G>T mutation in X-linked EDA1 was the unique one among six candidate genes (viz.PAX9, MSX1, AXIN2, WNT10A, EDAR and EDA1) associated with non-syndromic tooth agenesis known so far." (PMID 25203534, 2014). "Thus, in our whole patient cohort, severe tooth agenesis is explained in altogether 13 patients by mutations in PAX9 and in 11 by mutations in AXIN2." (PMID 23991204, 2013). "The association between AXIN2 rs2240308 with hypodontia was not significant." (PMID 31632692, 2019). "Mutations in two proteins of the destruction complex, AXIN-2 and APC, while both disabling β-catenin phosphorylation and promoting its nuclear localization, have completely opposite effects in humans: mutations in AXIN-2 lead to hypodontia, mutations in APC to hyperdontia." (PMID 25339911, 2014). "To date, mutations in AXIN2 (axis inhibition protein 2), EDA (ectodysplasin A), MSX1 (msh homeobox 1), PAX9 (paired box 9) and WNT10A (wingless-type MMTV integration site family, member 10a) have been demonstrated to be associated with non-syndromic tooth agenesis." (PMID 24278334, 2013). "The genetic basis of tooth agenesis is well-established, with several genes identified as controlling factors, namely MSX1, PAX9, AXIN2, EDA, IRF6, FGFR1, and WNT10A." (PMID 40040530, 2025). "Several genes, including MSX1, PAX9, AXIN2, WNT10A and EDA have been reported to involve in tooth agenesis." (PMID 33014315, 2020). "PAX9, MSX1, AXIN2, WNT10A and EDA have been experimentally established for congenitally missing teeth like hypodontia and oligodontia." (PMID 25203534, 2014). "In this study, we investigated four candidate genes MSX1, PAX9, AXIN2, and WNT10A in an Iranian family with hereditary non-syndromic tooth agenesis to find the variants responsible for tooth agenesis." (PMID 36561383, 2022). "In this family, Sanger sequencing detected no mutations in PAX9, AXIN2, MSX1, or WNT10A, which were previously reported as gene candidates for isolated tooth agenesis." (PMID 34545288, 2021). "Candidate genes, such as PAX9, MSX1, AXIN2, and EDA, are related to etiology of tooth agenesis." (PMID 25215247, 2014). "MSX1, PAX9, AXIN2, WNT10A, and EDA are proven candidate genes for familial tooth agenesis." (PMID 23227268, 2012).